AGMAT (agmatinase (putative))
Description:
Hydrolyzes linear guanidino acids to form urea and the corresponding amines. Displays specificity for substrates having a negatively charged head group and short chains including taurocyamine, guanidino propanoic and butanoic acids. May protect cells by detoxifying potentially harmful amounts of guanidino acids. Metabolizes L-arginine with low efficiency.
Synonyms: FLJ23384
Tractability: PROTAC: its protein half-life has been measured.
Gene: Protein-coding gene on chromosome 1 (15,571,699 to 15,585,078, reverse strand). Ensembl gene ENSG00000116771.
Subcellular location: Mitochondrion
Pathways (Reactome):
Metabolism: Agmatine biosynthesis
Gene Ontology:
Molecular function: arginase activity; guanidinobutyrase activity; guanidinopropionase activity; protein binding; agmatinase activity; hydrolase activity, acting on carbon-nitrogen (but not peptide) bonds, in linear amidines; metal ion binding
Biological process: agmatine biosynthetic process; urea cycle
Cellular component: mitochondrion
Genetic constraint (gnomAD): Loss-of-function variants: 37 observed, 28.29 expected, observed/expected ratio (o/e) 1.31, 90% interval 1 to 1.71. The upper end of that interval is the gene's LOEUF score, 1.71, which puts it in group 6 of 6, group 1 being the genes least tolerant of losing a copy. Missense variants: 497 observed, 451.54 expected, observed/expected ratio (o/e) 1.1, 90% interval 1.02 to 1.18. Synonymous variants: 199 observed, 180.45 expected, observed/expected ratio (o/e) 1.1, 90% interval 0.98 to 1.24.
Homologues: Orthologues: chimpanzee AGMAT (99% identical), macaque AGMAT (96% identical), dog AGMAT (87% identical), pig AGMAT (87% identical), mouse Agmat (84% identical), rabbit AGMAT (83% identical), rat Agmat (81% identical), tropical clawed frog agmat (73% identical), guinea pig AGMAT (66% identical), zebrafish agmat (64% identical), Caenorhabditis elegans argn-1 (15% identical). Paralogues in human: ARG2 (25% identical), ARG1 (22% identical).
Diseases named in the same sentence as AGMAT in open-access papers:
AGMAT is named in the same sentence as 18 diseases in open-access papers, as found by Europe PMC text mining. Sharing a sentence is not in itself a finding about the gene and the disease. The quoted sentences say what the papers report.
lung adenocarcinoma (4 papers, 2019 to 2024). A carcinoma that arises from the lung and is characterized by the presence of malignant glandular epithelial cells. "AGMAT is upregulated in lung adenocarcinoma tissues, which promotes tumorigenesis by activating MAPK and PI3K/Akt cascades, and patients with high levels of AGMAT have a poor prognosis." (PMID 37090117, 2023). "AGMAT could promote the lung adenocarcinoma tumorigenesis by activating the NO-MAPKs-PI3K/Akt pathway." (PMID 38978149, 2024). "Therefore, based on the combination of our results and the published literature, we speculate that AGMAT promotes iNOS expression and NO production by hydrolyzing agmatine, thereby promoting the development of lung adenocarcinoma." (PMID 31699997, 2019).
colorectal cancer (2 papers, 2016 to 2022). A primary or metastatic malignant neoplasm that affects the colon or rectum. "The results of coexpression analysis coupled to ENCODE ChIP-Seq data strongly suggest c-Myc and C/EBPβ as regulators of the expression of key enzymes of polyamine metabolism that are upregulated in colorectal cancer: SMOX, AZIN1, MTAP, SRM, AMD1, ODC1, and AGMAT." (PMID 27433286, 2016).
liver cancer (2 papers, 2023 to 2024). An epithelial or non-epithelial malignant neoplasm that arises from the liver. "Moreover, the importance of ARG1 and AGMAT expression in HCC patients is underscored by the finding that loss of ARG1 and/or AGMAT is associated with reduced survival based on a TCGA liver cancer dataset." (PMID 37804830, 2023). "Thus, while ARG1/AGMAT expression modulates arginine abundance and tumour growth in liver cancer, there appears to be additional metabolic complexity regarding the sources and sinks of arginine to be parsed in future work." (PMID 39871876, 2024). "To further investigate the role of unmetabolized arginine in HCC, we first screened a panel of human liver cancer cell lines for loss of ARG1, AGMAT, and arginine synthesis enzymes to find an in vitro experimental system that phenocopies L-dKO tumors, selecting the SNU-449 cell line." (PMID 37804830, 2023). "However, ARG1/AGMAT-controlled arginine levels impacted liver cancer cell metabolism beyond central energy metabolism." (PMID 37804830, 2023). "Immunoblotting confirmed loss of ARG1 and AGMAT and increased levels of RBM39 and ASNS in tumors of liver cancer patients compared to adjacent non-tumor tissue." (PMID 37804830, 2023). "To further investigate the hypothesis that unmetabolized arginine promotes growth of liver cancer cells, we cultured ARG1/AGMAT-expressing SNU-449 cells in the presence or absence of high levels of arginine or several arginine-related metabolites." (PMID 37804830, 2023).
colon cancer (1 paper, 2020). "In colon cancer, AGMAT promotes tumor progression by inducing chronic inflammation." (PMID 33282950, 2020).
gout (1 paper, 2022). A condition characterized by painful swelling of the joints, which is caused by deposition of urate crystals. "Three LD blocks existed in chromosome 1 for the variants relating to gout, which were composed of genes DNAJC16, AGMAT (first block), PDZK1, CD160, NUDT17 (second block), TRIM46, MUC1, MTX1, and ASH1L (third block)." (PMID 36221101, 2022). "Surprisingly, variants on chromosome 1, such as rs7546668 (DNAJC16), rs10927807 (AGMAT), rs9286836 (NUDT17), rs4971100 (TRIM46), rs4072037 (MUC1), and rs2974935 (MTX1), showed significant associations with gout in both discovery and replication cohorts (all p-values < 1e−8)." (PMID 36221101, 2022). "Surprisingly, the results showed that three variants of DNAJC16 and one variant of AGMAT were significantly associated with gout, which had not been found before, namely, rs7546668 (DNAJC16), rs12124078 (DNAJC16), rs7515244 (DNAJC16), and rs10927807 (AGMAT)." (PMID 36221101, 2022). "This study performed a GWAS in a large sample size and found genes DNAJC16, AGMAT, NUDT17, TRIM46 MUC1, and MTX1 on chromosome 1 relating to gout disease." (PMID 36221101, 2022). "Surprisingly, variants on chromosome 1 located in genes DNAJC16, AGMAT, NUDT17, TRIM46, MUC1 and MTX1 showed significant associations with gout, which finding had not been reported before." (PMID 36221101, 2022).
lung carcinoma (1 paper, 2020). "A recent study suggested that AGMAT could promote lung cancer progression by activating the NO-MAPKs-PI3K/Akt pathway." (PMID 33282950, 2020).
mood disorder (1 paper, 2020). A cognitive disorder a disturbance in which the person's mood is hypothesized to be the main underlying feature. "The enzyme agmatinase (encoded by the AGMAT gene), which acts on the substrate agmatine, has been implicated in the pathophysiology of mood disorders." (PMID 31960908, 2020).
pheochromocytoma (1 paper, 2025). "Then, we constructed amino acid metabolism profiles by WGCNA and LASSO regression model for investigating the impact of amino acid metabolism on pheochromocytoma pathogenesis and immunity and identified six hub genes (DDC, SYT11, GCLM, PSMB7, TYRO3, and AGMAT)." (PMID 38526709, 2025).
tumor (9 papers, 2019 to 2025). "Exosomal miR-33a suppresses putrescine biosynthesis by targeting AGMAT in cancer-associated fibroblasts (CAFs) from tumour core region, where putrescine inhibits the expression of demethylase KDM5C." (PMID 40903826, 2025). "Next, to determine if expression of ARG1 and AGMAT declines early in tumor development, we performed IHC on livers of 12- and 16-week-old L-dKO mice." (PMID 37804830, 2023). "An EdU cell proliferation kit, propidiumiodide staining, colony formation, cell migration, and invasion assays, and a xenograft tumor model were used to detect the biological function of AGMAT in LUAD." (PMID 31699997, 2019). "Our results obtained from LUAD are consistent with this finding, further supporting the tumor-promoting effect of AGMAT in various cancers." (PMID 31699997, 2019). "Compared with the normal group, the expression of DDC and SYT11 were remarkably up-regulated in the tumor group, while the expression of GCLM, PSMB7, TYRO3, and AGMAT were remarkably down-regulated in the tumor group." (PMID 38526709, 2025). "OAT, AGMAT, and SMS are only up-regulated in tumor tissue (Fig. 3a9, a12, a17, b6, b8, and b10), while ODC1 and SRM are highly expressed in tumor and lymphoid tissues (Fig. 3a13, a15, b7, and b9)." (PMID 37164975, 2023). "We also observed that overexpression of ARG1 or AGMAT after AAV injection was detected only in non-tumor liver tissue of L-dKO mice, whereas the few “escaper” tumors that appeared expressed low levels of ARG1 and AGMAT." (PMID 37804830, 2023). "Rbm39 knockdown reduced tumor burden in L-dKO mice, and as observed upon ARG1 or AGMAT overexpression and Asns knockdown, Rbm39 knockdown was detected only in non-tumor tissue." (PMID 37804830, 2023). "Furthermore, stably silencing AGMAT reduced the growth of NCI-H1975 and A549 tumor xenografts in mice." (PMID 31699997, 2019). "These facts led the authors to posit that arginine and polyamine pools are decoupled in liver tumours; the additional observation that driving ARG1/AGMAT expression did not affect tumour polyamine levels argues against polyamines representing a significant arginine sink in this context." (PMID 39871876, 2024).
cancer (5 papers, 2019 to 2025). A tumor composed of atypical neoplastic, often pleomorphic cells that invade other tissues. "This correlation between ARG1/AGMAT status and expression of the signature genes further supports the hypothesis that ARG1/AGMAT-controlled arginine levels determine cancer metabolism." (PMID 37804830, 2023). "Whether AGMAT inhibits the anticancer effect of agmatine by hydrolyzing agmatine, thereby exhibiting a cancer-promoting effect, will be the focus of our future research.NO/iNOS are closely related to the MAPK and PI3K/Akt pathways." (PMID 31699997, 2019). "In line with reported effects of arginine on glycolysis in cancers, we observed increased expression of glucose transporter 3 (GLUT3) and hexokinase 2 (HK2) in ARG1/AGMAT-expressing cells." (PMID 37804830, 2023). "We previously demonstrated that AGMAT was significantly overexpressed at the protein level in EAC compared to the patient-matched normal squamous esophagus and gastric tissue, and AGMAT has recently been described with a role in cancer by promoting tumorigenesis via MAPK signaling." (PMID 38604503, 2024).
AGMAT also shares sentences with these, for which no sentence is quoted: anxiety disorder (1 paper); Barrett esophagus (1); breast carcinoma (1); chronic lymphocytic leukemia (1); depression (1); gastric cancer (1); infection (1); ovarian carcinoma (1).